DCK (deoxycytidine kinase)
Diseases named in the same sentence as DCK in open-access papers (continued):
Sharing a sentence is not in itself a finding about the gene and the disease.
pancreatic cancer (continued). "A pancreatic cancer from a second patient who had relapsed on prior gemcitabine treatment but achieved a 30% reduction in tumour volume (partial response) within 3 cycles of NUC-1031 treatment, displayed low DCK expression." (PMID 31113993, 2019). "In addition, the statistical analysis indicated that dCK expression is negatively and significantly correlated with NRF2 expression in pancreatic cancer patients." (PMID 29701272, 2018). "Next, we analysed apoptosis by flow cytometry and found that dCK overexpression promoted apoptosis in PANC‐1 and MIA PaCa‐2 cells, indicating a negative role for dCK in pancreatic cancer proliferation." (PMID 29701272, 2018). "A novel finding of our study is the critical importance of DCK for gemcitabine sensitivity and thus any combination therapy using gemcitabine; pancreatic cancer cells without DCK are resistant to gemcitabine alone or in combination with entinostat." (PMID 28969017, 2017). "Several molecules involved in gemcitabine metabolism, including human equilibrative nucleoside transporter (hENT1), deoxycytidine kinase (dCK), and ribonucleotide reductase subunit M1 (RRM1), have been investigated as predictive biomarkers of gemcitabine efficacy, mostly in pancreatic cancer." (PMID 23710668, 2013). "Our data demonstrate for the first time that acquired and inherent chemoresistance of pancreatic cancer cells to gemcitabine is determined by the balance of dCK, RRM1, RRM2, and hENT1 gene expression, but not to that of any of the individual genes." (PMID 17224927, 2007). "However, DCK was only found deregulated in gemcitabine resistant pancreatic cancer cells, but not tumor samples." (PMID 34458141, 2021). "In pancreatic cancer, overexpression of reactive oxygen species (ROS)-detoxifying genes superoxide dismutase 2 (SOD2) and catalase (CAT) and downregulation of gemcitabine-metabolizing enzyme deoxycytidine kinase (DCK) confers cellular chemoresistance through exosome-derived miRNA-155." (PMID 33396739, 2020). "Furthermore, we found that expression of the dCK gene alone does not correlate with sensitivity to gemcitabine in eight pancreatic cancer cell lines." (PMID 17224927, 2007). "To determine whether the hENT1 × dCK/RRM1 × RRM2 ratio correlated with gemcitabine sensitivity, we examined the relative mRNA expression of hENT1, dCK, RRM1, and RRM2 to GAPDH in eight human pancreatic cancer cell lines." (PMID 17224927, 2007). "Although RRM1, dCK, and 5′-NT are useful predictors of GEM resistance, the individual actions of each of RR, dCK, and 5′-NT have not been reported as useful predictors of prognosis in pancreatic cancer chemotherapy." (PMID 22091436, 2011).
leukemia (24 papers, 2007 to 2025). A malignant (clonal) hematologic disorder, involving hematopoietic stem cells and characterized by the presence of primitive or atypical myeloid or lymphoid cells in the bone marrow and the blood. "The potential of 5-AC to overcome drug resistance to 5-AZA-CdR can be investigated by using a leukemia cell line deficient in deoxycytidine kinase." (PMID 24280679, 2012). "Additionally, mutations altering the levels of deoxycytidine kinase (DCK) can promote decitabine-resistant in leukemia cells." (PMID 34358067, 2021). "In addition, dCK-deficient leukemia cell lines and murine embryonic fibroblasts exhibited increased sensitivity to IR, indicating that pharmacologic inhibition of dCK may be an effective radiosensitization strategy." (PMID 25101980, 2014). "Taken together, these results suggest that DCTD plays a preeminent role in the metabolic activation of 5hmdC in human leukemia, and that high DCK expression can be utilized as a potential biomarker for therapeutic use of 5hmdC in human leukemia." (PMID 37378658, 2023). "All tested leukemia and lymphoma cells were capable of utilizing [15N3]dC for DNA synthesis, indicating that they possess a functional dCK-dependent salvage pathway." (PMID 35653193, 2022). "Targeting the remaining activities of RNR and dCK by specific inhibitors triggers lethal replication stress in vitro, suggesting a therapeutic opportunity for leukemia and potentially other cancers." (PMID 32722390, 2020). "In this study, we show that inhibition of deoxyribonucleoside salvage through the genetic deletion of dCK leads to enhanced radiosensitivity of a murine leukemia cell line and mouse embryonic fibroblasts." (PMID 25101980, 2014). "Building on the previous evidence, we demonstrated that in L1210 murine leukemia cell line the rate limiting enzyme in dN salvage, dCK, is activated via phosphorylation at Ser74 by ATM in response to oxidative stress and IR-induced DNA damage." (PMID 25101980, 2014). "We conclude that the absence of dCK contributes to the enhanced radiosensitivity of L1210-10K murine leukemia cells and MEFs derived from dCK KO mice." (PMID 25101980, 2014). "Our results show that IR induces significant changes in deoxycytidine metabolism by activating dCK and increasing the salvage of deoxycytidine from the extracellular space in L1210-10K murine leukemia cell line." (PMID 25101980, 2014). "It is well recognized that hematological malignancies, including many leukemias and lymphomas, express higher than normal levels of dCK and that this makes them more “sensitive” to nucleoside analog induced cell death." (PMID 24066967, 2013). "The level of dCK activity is one of the major factors determining the sensitivity of different leukemia and solid tumors to deoxynucleoside analogue toxicity." (PMID 23300702, 2012). "The authors hypothesized and confirmed that dCK was responsible for an important resistance mechanism to ATR inhibition in leukemia, as dCK activity could compensate for ATRi-induced downregulation of RNR." (PMID 37248212, 2023). "Previous translational studies showed a direct correlation between [18F]CFA accumulation and dCK expression in leukaemia cells, which could be blocked with a dCK inhibitor." (PMID 31656546, 2019). "Similarly, USF1 expression level was positively related with dCK gene, which was a well-documented DS leukemia-related gene." (PMID 29351810, 2018). "In sum, these results utilizing a murine leukemia cell line model and human A-T LCLs confirm that the activation of dCK in response to IR is ATM-dependent, and demonstrate that dCK activation is likely not carried out by functionally related serine/threonine kinases." (PMID 25101980, 2014).
leukemia (continued). "As dCK is responsible for intracellular phosphorylation of nucleosides to the active form, we evaluated the cytotoxicity of sapacitabine against the murine leukaemia cell lines L1210 and L1210dCK−, the latter was selected on the basis of resistance to continued passage in the presence of ara-C." (PMID 17637678, 2007). "However, it remains unknown what kinases are responsible for the remaining dCK pS74 present in VE-822-treated leukemia cells." (PMID 28808226, 2017). "We next sought to assess the anticancer efficacy of 5hmdC in human leukemia in relation to DCTD and DCK expression in various patient samples." (PMID 37378658, 2023). "To better understand contributions of DCK and UCK2 to dCTP and dTTP maintenance, we knocked DCK and UCK2 out of leukemia cells (HAP1) using CRISPR-Cas9 then measured levels of the deoxynucleotides." (PMID 32770088, 2021). "Our results provide quantitative insights into alterations of nucleotide biosynthetic pathways induced in leukemia cells by inhibiting ATR and rate-limiting de novo (RNR) and salvage (dCK) enzymes." (PMID 28808226, 2017). "To detect the transcription of DCK, CDA and SLC29A1, we examined mRNA expression of these genes in the leukemia blasts from the bone marrow of AML patients." (PMID 25398670, 2014). "This is in line with our observation that 5hmdC, the preferred substrate of DCTD, but not 5fdC, specifically inhibits colony formation in leukemia patient-derived bone marrow cells with high DCK expression." (PMID 37378658, 2023). "CNDAC-adapted AML sublines displayed pronounced cross-resistance to nucleoside analogues that are activated by DCK but not to anti-leukaemia drugs with other mechanisms of action." (PMID 34641952, 2021). "On the contrary, inhibition of the replication stress sensing kinase ataxia telangiectasia and Rad3-related protein (ATR) in leukemia cells down-regulates the activity of RNR and deoxycytidine kinase (dCK), rate-limiting enzymes of respectively the de novo and salvage dNTP synthesis pathways." (PMID 32722390, 2020). "In a murine leukemia cell line, we confirm that ATM phosphorylates dCK after IR at Ser74." (PMID 25101980, 2014). "Therefore, our combination of dT with the dCK inhibitor OR0642 to cotarget dNTP production by the SP, which is more efficient in killing tumor cells than either treatment alone, would be a better therapeutic approach for these leukemia patients." (PMID 37248212, 2023).
breast carcinoma (10 papers, 2012 to 2024). "The DCK gene, known for its increased expression in breast cancers with poor prognosis, is associated with the action of Decitabine, an FDA-approved drug for certain blood cancers, which has also been shown to significantly inhibit the growth of triple-negative breast cancer." (PMID 38745208, 2024). "DCK is also overexpressed in poor outcome breast cancers, including the metastatic CREB3L1-deficient breast cancer cell lines (HCC1954, BT474, SK-BR-3, MDA-MB-231, MCF7, and T47D) and has low expression in the non-tumorigenic breast cell line MCF10A12,33." (PMID 36123435, 2022). "In this study, we retrospectively evaluated the relationship between and the potential interaction of uPA and PAI-1, which are two members of the plasminogen/plasmin system, and the occurrence of dCK + cells in in a cohort of 481 breast cancer cases." (PMID 31307406, 2019). "This broad and very complex interaction between uPA, PAI-1, and dCK+ cells could explain the observed additive and maybe even synergistic effects of those three factors regarding outcomes of patients in early breast cancer stages." (PMID 31307406, 2019). "Another study found a correlation of cytotoxic response to decitabine and dF-dC in breast cancer cell lines; interestingly, the same report also identified higher dCK expression in breast cancer tissue from patients with poor outcome as compared to patients with good outcome." (PMID 30041457, 2018). "A long-term (>1 week) propagation of breast carcinoma cells lines with dCK knockdown revealed a significant reduction in their proliferation rates; however, the same dCK knockdown in normal human mammary epithelial cells (HMEC) or lung fibroblasts did not affect cell proliferation." (PMID 29257071, 2017). "Furthermore, identified six genes (TSPYL5, CD55, CCNE2, DCK, BBC3, and MUC1) susceptible to breast cancer were verified through the literature mining, GO analysis, and pathway functional enrichment analysis." (PMID 24073403, 2013). "We retrospectively analyzed a cohort of 480 breast cancer cases with known uPA/PAI-1 and dCK+ status." (PMID 31307406, 2019). "Using netSAM, we identified six novel genes (TSPYL5, CD55, CCNE2, DCK, BBC3, and MUC1) as cancer biomarkers for predicting survival and metastasis in patients with breast cancer." (PMID 24073403, 2013). "In addition, DCK has been found to be overexpressed in poor outcome breast cancer, suggesting that epigenetic therapy to induce CTA expression may prove to be an efficacious approach in breast cancer patients with poor prognosis." (PMID 23097673, 2012).
acute lymphoblastic leukemia (6 papers, 2012 to 2025). Leukemia with an acute onset, characterized by the presence of lymphoblasts in the bone marrow and the peripheral blood. "dCK inhibitors trigger replication stress alongside lethal DNA damage in tumor cells, and improve survival in mouse models of acute lymphoblastic leukemia (ALL) when administered alongside inhibitors of de novo dCTP synthesis, such as thymidine or triapine." (PMID 40519286, 2025). "CLA is selectively cytotoxic against acute lymphoblastic leukemia (CCRF-CEM cell line) and HL-60 cells, which have a high level of dCK and low levels of 5′-nucleotidase activity." (PMID 31575977, 2019). "Simultaneous targeting of dCK with the small molecule inhibitor DI-39 and RNR with dT in acute lymphoblastic leukemia (ALL) cancer cells induced replication stress and apoptosis confirming synergy between de novo dCTP inhibition and pyrimidine salvage inhibition." (PMID 35203388, 2022). "The highest dCK activity in acute monocytic leukemia cells was observed after incubation with CLA-FMOR and CLA-FPIR derivatives, whereas in acute promyelocytic and lymphoblastic leukemia cells, the highest activity was observed after incubation with a CLA-FMOR derivative." (PMID 31575977, 2019).
acute myeloid leukemia (6 papers, 2006 to 2025). Acute myeloid leukemia (AML) is a group of neoplasms arising from precursor cells committed to the myeloid cell-line differentiation. "Among them, inactivating DCK mutations have been identified in various cancer cell lines and acute myeloid leukemia patients that are resistant to pyrimidine nucleoside analogs." (PMID 38346958, 2024). "Moreover, dCK mRNA expression in leukaemic blasts at diagnosis was correlated with clinical outcome in patients with acute myeloid leukaemia treated with cytarabine." (PMID 16868547, 2006). "Interestingly, parallels exist between resistance mechanisms observed in TNBC and those described in hematologic malignancies such as myelodysplastic syndromes and acute myeloid leukemia, where reduced DCK activity and aberrant epigenetic regulator splicing contribute to DNMTi resistance." (PMID 41008798, 2025). "This negative modulation of ENT1 and dCK gene expression aligns with findings in the cytarabine-resistant HL-60 human leukemic cell line and in chemoresistant acute myeloid leukemia samples." (PMID 39339789, 2024).
ovarian carcinoma (6 papers, 2015 to 2026). A malignant neoplasm originating from the surface ovarian epithelium. "Diagnostic/pre-treatment levels of dCK have in a previous study been shown to predict in vivo gemcitabine sensitivity in human tumour xenografts (pancreas, colon, ovarian cancer)." (PMID 29695239, 2018). "This therapy was well tolerated by most platinum-resistant ovarian cancer patients, and patients with higher levels of baseline deoxycytidine kinase exhibited longer PFS." (PMID 33750444, 2021). "Ribonucleoprotein immunoprecipitation (RNP-IP) analysis of ovarian cancer cells in culture showed that cytoplasmic HuR increases deoxycytidine kinase (dCK), a metabolic enzyme that activates gemcitabine." (PMID 26943573, 2016). "Notably, eight proteins upregulated in the invasive stroma (NNMT, FCGR1A, FCER1G, TYMP, F13A1, DCK, CASP3, and SYK) represented FDA-approved drug targets outside of ovarian cancer, emphasizing their high relevance for future preclinical investigations." (PMID 41233595, 2026). "Gemcitabine, a novel nucleoside analogue that is activated by deoxycytidine kinase (dCK), has shown promising results in solid tumors such as nonsmall cell lung cancer and in pancreatic and ovarian cancers." (PMID 25866797, 2015).
cervical cancer (5 papers, 2012 to 2025). A primary or metastatic malignant neoplasm involving the cervix. "For instance, hypermethylation of the promoters of human equilibrative nucleoside transporter 1 (hENT1) and deoxycytidine kinase (dCK) confers gemcitabine resistance in cervical cancer." (PMID 40723396, 2025). "Cervical cancer cell lines were examined for the basal expression of hENT1, dCK, RRM1, RRM2, CDA genes and then their sensitivity to gemcitabine was evaluated." (PMID 22427797, 2012). "In this study, dCK expression in cervical cancer was elevated by radiation." (PMID 40263268, 2025). "A positive connection between dCK and ESR1 in cervical cancer was found using correlation analysis." (PMID 40263268, 2025). "Although dCK has been reported as a prognostic indicator in gastric cancer, liver cancer and meningioma, the correlation between survival and the joint expression of dCK and HSP90 in cervical cancer remains elusive." (PMID 40263268, 2025). "As a result of our research, we have concluded that dCK might be a new therapeutic target for increasing the radiosensitivity of HeLa cells and that HSP90 inhibitors might help to increase the effectiveness of radiation therapy for cervical cancer." (PMID 40263268, 2025).
lung cancer (5 papers, 2006 to 2024). A malignant neoplasm involving the lung. "Interestingly, a lung cancer from a partial responder, who had not been previously treated with gemcitabine and survived for 10 months while receiving NUC-1031, displayed high DCK expression." (PMID 31113993, 2019).
mastitis (5 papers, 2015 to 2025). Inflammation of breast tissue during lactation or postpartum due to an obstructed duct or infection. "Similarly, DCK gene was suggested as candidate gene associated with mastitis." (PMID 33535694, 2021). "A sequence-based association study of clinical mastitis to refine previously detected QTL regions suggested NPFFR2, SLC4A4, DCK, LIFR, and EDN3 as candidate genes for mastitis susceptibility." (PMID 27014337, 2016). "Moreover, strains isolated from the clinical mastitis group induced a higher expression of DCK compared to strains obtained from the other two groups." (PMID 40141146, 2025). "The comparison between these candidate QTL regions and known genes suggested that NPFFR2, SLC4A4, DCK, LIFR, and EDN3 may be considered as candidate genes for mastitis susceptibility." (PMID 26087655, 2015). "Therefore, NPFFR2, SLC4A4, DCK, LIFR, and EDN3 are candidate genes for susceptibility to mastitis." (PMID 26087655, 2015). "Furthermore, the comparison between these candidate QTL regions and known genes suggests that NPFFR2, SLC4A4, DCK, LIFR, and EDN3 may be considered as candidate genes for mastitis susceptibility." (PMID 26087655, 2015).
lymphoma (4 papers, 2013 to 2022). A malignant (clonal) proliferation of B- lymphocytes or T- lymphocytes which involves the lymph nodes, bone marrow and/or extranodal sites. "In 50% primary MCL samples, no change of DCK expression was observed at time of lymphoma relapse or progression." (PMID 24972933, 2014).
acute leukemia (3 papers, 2017 to 2024). A clonal (malignant) hematopoietic disorder with an acute onset, affecting the bone marrow and the peripheral blood. "Collectively our results quantify the control exerted by ATR on convergent nucleotide biosynthetic routes, and provide the rationale to co-target both signaling (ATR) and metabolic (RNR and dCK) mechanisms in acute leukemia for optimal therapeutic efficacy." (PMID 28808226, 2017). "We surmise that oncogenic addiction to proliferation of T-ALL blasts conveys a vulnerability to dCK inhibitors and positions OR0642 as a promising candidate to treat acute leukemias." (PMID 37248212, 2023). "In acute leukemias, VE-822 treatment resulted in reduced output from both RNR and deoxycytidine kinase (dCK) pathways of deoxynucleotide synthesis in ALL cells, with the combination of VE-822 with RNR and dCK inhibition (with 3-AP and DI-82, respectively) being lethal." (PMID 38347838, 2024).
colon carcinoma (3 papers, 2006 to 2020). "Furthermore, transcription analysis in untreated cells suggested the predictive value of expression of both hENT1 and dCK, while, as previously reported in lung and colon cancer cells, a similar correlation was found between TS and chemoresistance to pemetrexed." (PMID 16868547, 2006).